SERPINH1 (serpin family H member 1)
Description:
Binds specifically to collagen. Could be involved as a chaperone in the biosynthetic pathway of collagen.
Synonyms: AsTP3; CBP1; CBP2; HSP47; SERPINH2; PIG14; OI10; PPROM; RA-A47; gp46
Tractability: Antibody: UniProt predicts a signal peptide or a membrane-spanning region. PROTAC: ubiquitination databases record sites on it; its protein half-life has been measured; a small molecule that binds it is known.
Target class: Other cytosolic protein
Gene: Protein-coding gene on chromosome 11 (75,561,564 to 75,572,787, forward strand). Ensembl gene ENSG00000149257.
Subcellular location: Endoplasmic reticulum lumen
Subcellular location (Human Protein Atlas): Endoplasmic reticulum
Pathways (Reactome):
Cellular responses to stimuli: Attenuation phase; HSF1 activation; HSF1-dependent transactivation; Regulation of HSF1-mediated heat shock response
Extracellular matrix organization: Collagen biosynthesis and modifying enzymes
Gene Ontology:
Molecular function: protein binding; RNA binding; collagen binding; serine-type endopeptidase inhibitor activity; protein folding chaperone
Biological process: collagen fibril organization; response to unfolded protein; protein folding
Cellular component: endoplasmic reticulum; endoplasmic reticulum-Golgi intermediate compartment; extracellular matrix; membrane raft; endoplasmic reticulum lumen; cytoplasm
Genetic constraint (gnomAD): Loss-of-function variants: 20 observed, 29.94 expected, observed/expected ratio (o/e) 0.67, 90% interval 0.47 to 0.97. The upper end of that interval is the gene's LOEUF score, 0.97, which puts it in group 4 of 6, group 1 being the genes least tolerant of losing a copy. Missense variants: 543 observed, 590.29 expected, observed/expected ratio (o/e) 0.92, 90% interval 0.86 to 0.99. Synonymous variants: 251 observed, 252.59 expected, observed/expected ratio (o/e) 0.99, 90% interval 0.9 to 1.1.
Homologues: Orthologues: chimpanzee SERPINH1 (100% identical), macaque SERPINH1 (99% identical), dog SERPINH1 (97% identical), pig SERPINH1 (97% identical), guinea pig SERPINH1 (96% identical), mouse Serpinh1 (95% identical), rat Serpinh1 (94% identical), tropical clawed frog serpinh1 (74% identical), zebrafish serpinh1b (65% identical), zebrafish serpinh1a (64% identical). Paralogues in human: SERPINB1 (25% identical), SERPINB12 (25% identical), SERPINB6 (24% identical), SERPINB8 (24% identical), SERPINB9 (24% identical), SERPINA5 (24% identical), SERPINB3 (23% identical), SERPINB5 (23% identical), SERPINA1 (23% identical), SERPINB4 (23% identical), SERPINB10 (23% identical), SERPINB2 (23% identical), and 24 more.
Diseases named in the same sentence as SERPINH1 in open-access papers:
SERPINH1 is named in the same sentence as 199 diseases in open-access papers, as found by Europe PMC text mining. Sharing a sentence is not in itself a finding about the gene and the disease. The quoted sentences say what the papers report.
glioma (31 papers, 2008 to 2025). A benign or malignant brain and spinal cord tumor that arises from glial cells (astrocytes, oligodendrocytes, ependymal cells). "Besides, the downregulation of miR-29 was found to be associated with the upregulation of SERPINH1 in various cancers (glioma, cervical, breast, and renal), being involved in the growth, proliferation, migration, and invasion of cancer cells." (PMID 35118144, 2021). "As a prognostic biomarker in glioma, SERPINH1 is involved in tumor progression through pathways such as JAK-STAT and modulates the immune microenvironment." (PMID 40530702, 2025). "Acting as an oncogene in glioma, SERPINH1 promotes tumor growth and invasion, while its inhibition suppresses cell proliferation, migration, and invasion, and induces apoptosis." (PMID 40530702, 2025). "In low-grade glioma and renal cell carcinoma, SERPINH1 is involved in extracellular matrix remodeling, thereby promoting tumor metastasis." (PMID 40705756, 2025). "While mutations in EFEMP2, ADAM10, SERPINH1, ADAM15, GAS6 and TNXB were detected only in patients with glioma grade 3, mutations in LTBP2, DCN, CRELD1 and HAPLN3 were observed only in patients with glioma grade 4, GBM." (PMID 38272115, 2024). "In gliomas SERPINH1 overexpression was correlated to a poor overall survival and to a reduced progression free rate due to the promotion of GBM invasion, angiogenesis and stemness." (PMID 38272115, 2024). "Different studies presented that in numerous cancers, including glioma, pancreatic cancer, cervical and lung cancer, the expression level of SERPINH1 rises." (PMID 36415513, 2022). "SERPINH1 expression is related to the malignancy of glioma and promotes angiogenesis in glioma through autocrine and paracrine mechanisms." (PMID 33579282, 2021). "SERPINH1 also correlates with the grade of glioma, and regulates proliferation, migration and invasion of glioma cell lines." (PMID 32091407, 2020). "Numerous studies have demonstrated that SERPINH1 is overexpressed in various human cancers, including lung cancer, pancreatic cancer, cervical cancer and glioma." (PMID 31249732, 2019). "The overexpression of SERPINH1 was found in many different cancers, including lung cancer, cervical squamous cancer, and glioma." (PMID 29921304, 2018). "MiR-29a refrained from glioma tumor growth and invasion through decreasing the expression of HSP47, also known as SERPINH1." (PMID 29217524, 2018). "Moreover, MRI inputs integrated into machine learning models can predict genomic features and differentiate between low- and high-grade gliomas by identifying markers such as B2M, SRPX2, and SERPINH1." (PMID 40806525, 2025). "Another similar hub gene Serpin family H member 1 (SERPINH1), also known as HSP47, was proved to promote GBM stem-like cell survival by modulating tumor microenvironment through TGF-β pathway and enhance glioma angiogenesis through HIF1α-VEGFR2 signaling." (PMID 34868960, 2021).
liver fibrosis (29 papers, 2007 to 2026). "The authors analyzed 588 overlapping and differentially expressed genes altered in RAP-8-treated mice with CCl4-induced liver fibrosis and identified cell cycle-associated genes (Cenpp, Cyp2c55, and Serpinh1) as relevant targets for treating liver fibrosis." (PMID 37627244, 2023). "The inhibition of SERPINH1 effectively suppresses collagen secretion, leading to a notable amelioration of liver fibrosis in mice." (PMID 40702440, 2025). "This study also verified that targeting SERPINH1 can effectively reduce liver fibrosis, but its effect on hepatitis is not obvious." (PMID 39430252, 2024).
breast cancer (27 papers, 2015 to 2025). A primary or metastatic malignant neoplasm involving the breast. "The upregulated of SERPINH1 was associated with poor prognosis in breast cancer, stomach adenocarcinoma, and esophageal carcinoma." (PMID 35058967, 2021). "Furthermore, SERPINH1 expression was associated with poor prognosis in patients with breast cancer, stomach adenocarcinoma, and esophageal carcinoma." (PMID 36700224, 2022). "Cervical cancer, breast cancer, glioblastoma, and colorectal cancer all have abnormal expression of SERPINH1." (PMID 41244835, 2025). "SERPINH1 encourages breast cancer cell metastasis and invasion by influencing the levels of various extracellular matrix (ECM) proteins." (PMID 41244835, 2025). "SERPINH1, also known as HSP47, is noteworthy in the development of several kinds of human malignancies, including breast cancer, cervical cancer and other malignancies." (PMID 39170698, 2024). "Specific macrophage subsets co-expressing CD206 and SERPINH1 or MORC4 were connected with positive patient prognosis in breast cancer." (PMID 38893266, 2024). "Of note, SERPINH1, involved in both up-regulated hubs, exhibits an oncogenic role in breast cancer, where it acts to promote deposition of specific collagens and fibronectin." (PMID 36169805, 2022). "For Serpinh1, also known as Hsp47, expression activation was reported during breast cancer development and progression." (PMID 36151122, 2022). "In the human breast cancer tissue, SERPINH1 was positively correlated with collagen I, collagen IV, and fibronectin expression." (PMID 35118144, 2021). "SERPINH1 is aberrantly expressed in cervical cancer, breast cancer, glioblastoma and colorectal cancer." (PMID 32091407, 2020). "SERPINH1 promotes invasion and metastasis of breast cancer cells by regulating the expression of several extracellular matrix (ECM) proteins." (PMID 32091407, 2020). "The presence of CD206+ macrophages correlated with a pronounced lymphocyte infiltrate and subsets of CD206+ macrophages, expressing SERPINH1 and collagen 1, or MORC4, were unexpectedly associated with improved survival of breast cancer patients." (PMID 33377644, 2020). "In breast cancer, SERPINH1 is a hub gene of ECM transcription network and promotes tumor growth." (PMID 34194496, 2021). "Indeed, we detected an induction of SERPINH1 after a 96‐hour co‐culture with a number of breast cancer cell lines, which was statistically significant for MCF‐7 and T47D cells." (PMID 33377644, 2020). "Examples include miR‐30c‐2‐3p in breast cancer, miR‐218 in hepatocellular carcinoma, CXCL14 in colorectal carcinoma, and SERPINH1 in clear cell renal cell carcinoma." (PMID 30913346, 2019). "CD79A, SERPINH1, KCNJ5 and TMEM14C exhibited breast cancer subtype–independent overall survival differences." (PMID 25572802, 2015). "Taken together, our data indicate that expression of MORC4, SERPINH1, and MHCII at protein level in combination with CD206 may serve as macrophage markers for survival in mammary carcinoma." (PMID 33377644, 2020).
gastric cancer (27 papers, 2009 to 2025). A primary or metastatic malignant neoplasm involving the stomach. "SERPINH1: The demonstration that SERPINH1 expression in gastric cancer is associated with lymph node metastasis and poor survival outcomes has been well-documented." (PMID 40951343, 2025). "The aberrant expression of the SERPINH1 gene has been shown to be closely linked to tumor growth, invasion, and metastasis in cervical squamous cell carcinoma and gastric cancer." (PMID 37760828, 2023). "SERPINH1 can promote survival, invasion, and migration of human gastric cancer SGC7901 cells via the Wnt/β-catenin signaling pathway." (PMID 34457026, 2021). "Suppression of SERPINH1 in gastric cancer cells is known to reduce survival, colony formation, migration, and invasion, whereas overexpression enhances these traits." (PMID 34503200, 2021). "Association between the expression of circulating COL6A3, SERPINH1 and PLEKHG1 in gastric cancer and clinicopathologic characteristics." (PMID 31249732, 2019). "For early stomach cancer, the best three 1-gene discriminators are also SERPINH1, BGN and COL12A1, respectively." (PMID 21060876, 2010). "Similarly, the role of the Wnt/β-catenin signaling pathway in gastric cancer has been demonstrated by a study showing that SERPINH1 promotes the proliferation and metastasis of gastric cancer cells by activating this pathway." (PMID 41138746, 2025). "For example, lncRNA H19, which is abnormally expressed in gastric cancer, influences the infiltration of cancer-associated fibroblasts (CAFs), macrophages, CD4+T cells, and CD8+T cells in the TME through the miR-378a-5p/SERPINH1 axis, thereby promoting the progression of gastric cancer." (PMID 41229433, 2025). "In scirrhous gastric cancer tissues and cells, SERPINH1 protein is localized in the ECM." (PMID 32091407, 2020). "In addition, serum SERPINH1 has been reported to be used as a possible target for patients with scirrhous gastric cancer." (PMID 31249732, 2019). "Serpin family H member 1 (SERPINH1) is a member of the serpin superfamily of serine proteinase inhibitors and binds specifically to collagen, has been identified acting in gastric cancer metastasis and proliferation and migration of retinal endothelial cells." (PMID 37621558, 2023). "The regulation of EMT by the Wnt signaling pathway has been determined including Wnt5a, FOXP3, SERPINH1, CUL4B, and SUFU, which can be used in BLCA, gastric cancer, and pancreatic cancer." (PMID 34579753, 2021). "SERPINH1 has been shown to play a role in epithelial-mesenchymal transition (EMT) and metastasis in gastric cancer." (PMID 34885041, 2021). "In this study, we investigated the role of SERPINH1 in gastric cancer (GC) progression." (PMID 32091407, 2020). "The best three single-gene discriminators are SERPINH1, BGN and COL12A1 for stomach cancer, having 99.1%, 98.2% and 98.2% classification accuracy on the training set and 94.2% and 96.7%, 88.4% and 93.3%, and 84.1% and 75.8% on the two test sets, respectively." (PMID 21060876, 2010). "Specifically, SERPINH1 could regulate EMT and metastasis of gastric cancer via the Wnt/β-catenin signaling pathway." (PMID 37091161, 2023). "The results revealed that exosomal AGT, SERPINH1 and MMP7 may serve as biomarkers for gastric cancer diagnosis and prognosis and involved in GC progression." (PMID 34215253, 2021). "The topmost molecular network in the intestinal subtype on IPA network analysis showed increased expression of SULF1, HGF, SPARC, SERPINH1, and IGFBP7, which have been shown to contribute to the growth and survival of tumor cells, tumor invasion, metastasis, and poor survival in gastric cancer." (PMID 34885041, 2021).
pulmonary fibrosis (25 papers, 2005 to 2026). Chronic progressive interstitial lung disorder characterized by the replacement of the lung tissue by connective tissue, leading to progressive dyspnea, respiratory failure, or right heart failure. "SERPINH1 has been implicated in several collagen-related diseases, such as, brittle bone disease, keloid scars, and lung fibrosis." (PMID 32091407, 2020). "Sephin1, a small-molecule inhibitor of PPP1R15A, increased collagen 1a and Serpinh1 mRNA expression levels in mice with bleomycin-induced pulmonary fibrosis compared to the corresponding levels in control mice." (PMID 37760828, 2023). "RT-PCR also demonstrated an increase in Serpinh1 mRNA expression, and the relative amount of Serpinh1 mRNA correlated significantly with lung hydroxyproline content, an indicator of pulmonary fibrosis in bleomycin-treated lungs." (PMID 37760828, 2023). "Morphological pulmonary fibrosis, hydroxyproline levels, inflammatory cytokines in the lungs, and the number of inflammatory cells in the bronchoalveolar lavage fluid of bleomycin-treated rats were significantly suppressed by Serpinh1 siRNA." (PMID 37760828, 2023). "The relevance of its mechanism of action for pulmonary fibrosis is unclear; nintedanib has been reported to reduce SERPINH1 mRNA levels but not HSP47 protein levels in TGF-β1–treated IPF fibroblasts in vitro." (PMID 37760828, 2023).
osteogenesis imperfecta (23 papers, 2009 to 2025). Osteogenesis imperfecta (OI) comprises a heterogeneous group of genetic disorders characterized by increased bone fragility, low bone mass, and susceptibility to bone fractures with variable severity. "A missense mutation in SERPINH1 has been shown to cause severe recessive osteogenesis imperfecta which is a connective tissue disorder characterized by low bone mass, bone fragility and susceptibility to fractures after minimal injury." (PMID 33687501, 2021). "A loss-of-function alteration in SERPINF1 has been demonstrated to cause osteogenesis imperfecta type VI in humans while variants in SERPINH1 have been associated with ostogenesis imperfecta in both humans and dogs." (PMID 25875171, 2015). "Besides collagen type II, HSP47 is also crucially involved in the maturation of other types of procollagens such as type I. Consistently, missense mutations in the HSP47 encoding gene SERPINH1 cause a recessive form of osteogenesis imperfecta." (PMID 41278200, 2025). "Indeed, homozygous missense mutations in the SERPINH1 gene result in osteogenesis imperfecta and mice deficient for SerpinH1 die shortly after birth, exhibiting generalised chondrodysplasia and bone abnormalities." (PMID 33843993, 2021). "We further explored the disease network of SERPINH1, in which SERPINH1 was highly enriched in osteogenesis processes such as osteogenesis imperfecta." (PMID 37091161, 2023). "The inhibitor for SERPINH1 has been noted in mature human drug targets and has been commercialized for treatment of osteogenesis imperfecta." (PMID 32024063, 2020).
pancreatic cancer (14 papers, 2009 to 2023). "We propose a specific assay based on PTK7 and SERPINH1 detection by immunohistochemistry to better characterize pancreatic carcinoma invasiveness and prognosis." (PMID 36587397, 2023). "After analyzing the PPI network of genes related to GLUT1, we found that GIPC1 54, 55, and SERPINH1 56, 57 were related to the mechanism of tumor metastasis, including in pancreatic tumors." (PMID 35711842, 2022). "Pancreatic cancer cell lines ectopically expressing PDX1 in our study had a decreased level of SERPINH1, a positive regulator of cell motility." (PMID 34503200, 2021). "While studies have already shown that SERPINH1 is a stromal marker and confers chemoresistance, our study identified PTK7 as a novel marker of fibroblasts in invasive pancreatic carcinomas." (PMID 36587397, 2023).
colorectal cancer (13 papers, 2019 to 2025). A primary or metastatic malignant neoplasm that affects the colon or rectum. "Previous research studies have shown that SERPINH1 is aberrantly expressed in a variety of cancers, for example, the expression of SERPINH1 is significantly increased in colorectal cancer cells." (PMID 36105106, 2022). "SERPINH1 protein expression was significantly higher in colorectal cancer patients with lymph node metastasis." (PMID 32091407, 2020).
lung carcinoma (10 papers, 2018 to 2024). "The result showed that the SERPINH1 protein levels were higher in tissues of colon, liver, and lung cancer than in corresponding normal tissues." (PMID 36105106, 2022). "For the protein information of SERPINH1, the result demonstrated that SERPINH1 protein level was higher in tissues of colon, liver, and lung cancer." (PMID 36105106, 2022).
lymph node metastasis (9 papers, 2012 to 2025). "GC patients with high SERPINH1 expression are associated with lymph node metastasis and poor prognosis." (PMID 32091407, 2020). "The higher COL6A3 level was significantly associated with increased lymph node metastasis (P = 0.0233), whereas the elevated expression of SERPINH1 was associated with advanced age (P = 0.0034) and poor differentiation (P = 0.0231) in GC patients." (PMID 31249732, 2019). "A higher COL6A3 level was also significantly correlated with lymph node metastasis and poor prognosis in GC patients, while high levels of SERPINH1 and PLEKHG1 mRNA expression were correlated with lower overall survival (OS) in GC patients." (PMID 35892889, 2022).